MMP2 (matrix metallopeptidase 2)
Diseases named in the same sentence as MMP2 in open-access papers (continued):
Sharing a sentence is not in itself a finding about the gene and the disease.
cancer (continued). "Cancer cells rely on the overexpression of MMP2 and MMP9 to migrate from the source cells to adjacent tissues during these processes." (PMID 40136519, 2025). "Short-term co-culture of cancer cells and adipocytes induces upregulation of MMP2 in MCF7 cells, enhancing their invasiveness." (PMID 40841364, 2025). "Melatonin supplementation has been reported to be effective in increasing MMP2 activity in gastric ulceration and decreasing MMP2 expression in cancer stem cells and SKOV3 cells." (PMID 39796199, 2025). "An increase in C–C motif chemokine ligand 5, MMP-2/9, transforming growth factor-β, and vascular endothelial growth factor levels by TAMs promotes cancer cell invasion, epithelial–mesenchymal transition, and angiogenesis, respectively." (PMID 40722951, 2025). "MMP-2 has also expressed great significance in the field of detection of various cancers, such as pancreatic, colorectal, brain, prostate cancer, and ovarian cancer." (PMID 41002342, 2025). "This activation promotes phosphorylation of Akt and mTOR, subsequently enhancing the activity of MMP2, a critical enzyme driving cancer cell invasiveness." (PMID 40333816, 2025). "Activated p70S6K1 has been shown to promote the expression of MMP2/9, leading to the degradation of the extracellular matrix and facilitating cancer cell migration." (PMID 40422575, 2025). "Previous studies have shown that autophagy promotes the secretion of protumorigenic factors—including IL-6, IL-8 and MMP2—in Ras-driven cancers and facilitates IL-1β secretion through unconventional secretory pathways." (PMID 41408407, 2025). "Elevated levels of MMP-2 and MMP-9 have been implicated in the progression and metastasis of various cancers, including those of the bladder, breast, cervix, colon, and others." (PMID 40563423, 2025). "This Twist1 is known to play a critical role in promoting EMT by activating key target genes such as MMP2 (Matrix Metalloproteinase 2) in cancers." (PMID 40136629, 2025). "Computational approaches, including molecular docking and molecular dynamics simulations, revealed a strong and stable interaction between δ-cadinene and MMP-2, a key protein involved in cancer invasion." (PMID 40940940, 2025). "Research indicates that curcumin inhibits the migration and invasion of cancer cells by suppressing matrix metalloproteinases (MMP-2) and (MMP-9), which are enzymes that facilitate cancer spread by degrading the extracellular matrix." (PMID 40918117, 2025). "Western blot analysis of MMP-2 and MMP-9, proteins associated with cancer invasion and metastasis, aligned with the Transwell results." (PMID 39508798, 2025). "Several studies have indicated that MMP2/MMP9 is an important prognostic factor for various cancer types." (PMID 40735254, 2025). "The upregulation of MMP-2 is observed in various tumors, and its elevation facilitates the proliferation, motility, and metastasis of malignant tumor cells." (PMID 40894070, 2025). "Next, the expression profiles of CD44, FGF2, FGF10, KDM6A, FN1, and MMP2 were evaluated using the OcoDB database across different clinical stages, age groups, and racial categories in cancer patients." (PMID 39833941, 2025). "MMP‐2, a matrix metalloproteinase, degrades the main component of the basement membrane (type IV collagen), thereby promoting the metastasis of cancer cells." (PMID 40895140, 2025). "With respect to the diagnostic biomarkers, we detected significantly higher serum levels of CA125, HE4, IL-6, IL-8, G-CSF, SAA, MRP8/14, OPN, MMP9, and MMP2 in women with benign or malignant tumors than in healthy controls." (PMID 41149076, 2025). "It has been shown to prevent cancer cells from migrating and invading by decreasing the production of MMP-2/MMP-9, which is needed to degrade the extracellular matrix." (PMID 40667502, 2025). "In the early stages of cancer progression, MMP2 expression was upregulated in the peri- and outer regions." (PMID 39965034, 2025).
cancer (continued). "Beyond dystrophic conditions, MMP2 and MMP14 have been implicated in cardiac fibrosis and muscle remodeling associated with cancer cachexia." (PMID 40966415, 2025). "Matrix metalloproteinase 2 (MMP2) is a zinc-dependent endopeptidase that has been implicated in numerous biological processes, including tissue remodeling, angiogenesis, and cancer metastasis." (PMID 40533843, 2025). "The results position miR-125b-5p as a dual-action biomarker and therapeutic target against MMP-2-driven LC metastasis, offering new insights into critical inflammation-to-cancer connections." (PMID 41155277, 2025). "ECN exhibited a strong anti-invasive effect, as its non-toxic doses significantly suppressed the TGF-β1-induced invasion of NSCLC cells through Matrigel and decreased the secretion of MMP-2 from these cancer cells." (PMID 40806251, 2025). "In response, activated astrocytes produce inflammatory cytokines, such as TNF and IL-6, which stimulate cancer cells and promote MMP-2 and MMP-9 secretion via the action of urokinase-type plasminogen activator (uPA)." (PMID 41429896, 2025). "MMP-2 is a protease that can be secreted by cancer cells to degrade collagen components in the ECM, which facilitates cancer invasion." (PMID 40806251, 2025). "CXCR4+ cancer stem cells also show increased tumor invasion and cell migration, via the activation of Rac1 and MMP-2/MMP-14 proteinases and enhanced angiogenesis by triggering cancer cell adhesion to endothelial cells and upregulation of VEGF/VEGFR." (PMID 40307933, 2025). "MMPs are involved in the migration or invasion process of various cell types, including VSMCs or cancer cells, and it has been reported that the expression of MMP2 and MMP9 in the extracellular matrix of blood vessels promotes the migration of VSMCs." (PMID 41008632, 2025). "The liposomal complex inhibited invasion and metastasis by lowering the levels of VE-Cadherin, PI3K, VEGF, HIF-1α, FAK, and MMP-2, thereby inducing apoptosis in cancer cells." (PMID 40427522, 2025). "The study found that RA suppresses epithelial-mesenchymal transition (EMT), a crucial step in cancer metastasis, by upregulating miR-506 and suppressing MMP2 and MMP16." (PMID 40427522, 2025). "For the first time, we report the cytotoxic effect of the metabolite δ-cadinene in triple-negative BC, identifying MMP-2 as one of its potential molecular targets that contributes to a significant reduction in cancer cell invasion." (PMID 40940940, 2025). "The In Silico molecular docking analysis confirmed that Thymoquinone strongly interacted with key cancer targets like MMP2, AKT, PTEN and VEGFR2 with least binding energy than standard drug, Busulfan." (PMID 40504815, 2025). "In several clinical trials targeting MMP2, drugs such as Marimastat (BB-2516), Prinomastat (AG3340), and Tanomastat (BAY 12-9566) were designed to inhibit MMP2 activity with the aim of suppressing cancer progression." (PMID 40303286, 2025). "Several studies have looked at the interaction of eHSP90α and MMP-2 in cancer cells by studying higher endogenous levels in aggressive cancer cell lines, exogenous gene expression, or adding recombinant protein to culture medium." (PMID 41509368, 2025). "The interplay between TIMP2 and Aha1 regulates the extracellular MMP2:HSP90 complex, with TIMP2 serving to disrupt MMP2 activity, thus influencing cancer progression." (PMID 41369326, 2025). "Taken together, these findings suggest that the OCT4-DUSP6 axis promotes cancer cell migration and invasion by upregulating MMP-2 and MMP-9 through a Notch-dependent, MAPK-independent mechanism, highlighting its potential role in NSCLC progression." (PMID 41210685, 2025).
cancer (continued). "In this type of cancer, it has been observed that an increase in the ERα: ERβ expression ratio induces an increase in MMP2 expression, modulating cancer invasion." (PMID 41301715, 2025). "In line with this, GHRH antagonists of the MIA class have been shown to impede cancer cell migration and invasion by preserving E-cadherin expression and inhibiting MMP2 and MMP9 expression and activity." (PMID 40244089, 2025). "Molecular docking revealed stronginteractions of sarcorine C and salonine C with key cancer-associatedproteins (CDK2, KRAS, CYP17A1, Bcl-2, MMP-2, and NOS)." (PMID 41141772, 2025). "On the other hand, degrading the fibronectin matrix by matrix metalloproteinase 2 (MMP-2) promotes cancer cell outgrowth." (PMID 40568095, 2025). "MMP2 is correlated with poor prognosis in cancers, and the ERK pathway can regulate MMP2 expression." (PMID 40501228, 2025). "Decreased MMP-2 expression has been related to reduced proliferation, clonal growth, and metastasis of cancer cells." (PMID 40141020, 2025). "Two enzymes among the MMPs, MMP-9 and MMP-2 (gelatinases), play a key role in several types of cancer." (PMID 40141020, 2025). "The matrix metalloproteinase family, including MMP1, MMP2, and MMP9, causes cancer cell invasion and migration during cancer progression." (PMID 40093316, 2025). "The zinc matrix metalloproteinases (including MMP-2) are involved in the propagation of various types of cancers, including the breast." (PMID 40507273, 2025). "The contrasting roles of CD44 and MMP2 in proliferation and migration emphasize the complexity of gene functions in cancer." (PMID 39833941, 2025). "The dose-dependent suppression of ECFC migration, invasion, and tube formation extends earlier observations of POE inhibiting cancer cell motility via downregulation of MMP-2/9 and induction of autophagy." (PMID 40981364, 2025). "Our study is the first to demonstrate that ECN inhibits cell migration, MMP-2 secretion, and invasion of human NSCLC cell lines, providing insights into the underlying mechanisms through regulating the EMT program in cancer cells." (PMID 40806251, 2025). "Transcriptomic and proteomic analyses showed downregulation of migration- and invasion-related genes in cancer cells, and Western blot analysis confirmed reduced expression of MMP2, MMP9, and N-cadherin." (PMID 41226554, 2025). "The overexpression and secretion of MMP-2 and MMP-9 is increased in several types of human cancers and is associated with poor prognosis." (PMID 39941886, 2025). "MMP‐2 plays a pivotal role in cancer progression, invasion, and metastasis, influencing various stages of the metastatic cascade, including intravasation, extravasation, and pre‐metastatic niche remodeling." (PMID 40079158, 2025). "In cancer, MMP2 is frequently overexpressed, and elevated protein levels correlate with adverse prognostic factors, such as poor differentiation, metastasis to secondary organs, and resistance to chemotherapy." (PMID 40079158, 2025). "Specifically, MMP-2, -3, -9, and -14 are often upregulated and linked to ECM remodeling in multiple cancer types." (PMID 39811640, 2025). "MMP‐2, which has been identified as a hub in the networks, plays a critical role in cell invasion across different cancer types." (PMID 40079158, 2025). "The results of the bioinformatic study are with a network pharmacology approach on the cancer pathway of bioactive compounds from each isolate target the matrix metalloproteinase-2 (MMP-2) protein." (PMID 40687624, 2025). "MMPs, including MMP-9 and MMP-2, play a role in cancer cell invasion, tumor growth, and the facilitation of metastasis." (PMID 40989799, 2025). "In conditions of upregulation, the functional co‐expression of ionic channels and MMP‐2 enhances the migratory and invasive capacities in cancer." (PMID 40079158, 2025).
cancer (continued). "As expected, ZNF24 mRNA and protein levels were down-regulated in CRC compared with that of adjacent carcinoma, while the expression level of MMP2 in CRC was significantly up-regulated compared with that of adjacent carcinoma." (PMID 40520987, 2025). "Among the cancer cases, MMP2 expression is evenly split, with 50% (45 cases) showing low expression and 50% (45 cases) showing high expression." (PMID 38978899, 2024). "Regarding cancer biomarkers, Ki67, MMP2, and MMP9 protein levels were decreased by SAMD5 but increased by PLK1; PLK1 overexpression significantly alleviated the inhibitory effects of SAMD5 on these factors." (PMID 39524172, 2024). "Increased MMP2 levels have been found to trigger the proliferation and metastasis of breast, ovarian, and lung cancers." (PMID 38584845, 2024). "Similar to the cancer tissue samples, a significant weak positive correlation was also seen between MMP2 and PDPN and between THY1 and PDPN in adjacent normal tissues." (PMID 39335130, 2024). "MMP-9 and MMP-2 are the principal proteolytic enzymes that promote cancer cell invasion by decomposing the basement membrane and then triggering cancer metastasis." (PMID 38904007, 2024). "In a cisplatin-resistant OSCC cell line, non-toxic concentrations (50 μM) of resveratrol depleted the migration and invasive capabilities of cancer cells by reducing the mRNA and protein expression of MMP-2 and MMP-9." (PMID 39335164, 2024). "This would be in line with studies indicating that the MMP14-generated sBSG fragment, released by cancer cells, acts to induce MMP2 activity in neighboring fibroblasts." (PMID 38892056, 2024). "Taken together, these data show that HMHA1 augments cancer cell invasion in an MMP-2/-9-dependent manner." (PMID 38740970, 2024). "In the search for more promising therapies, matrix metalloproteinases have become of significant interest, such as MMP-1, MMP-2, MMP-9, and MMP-13, which have been linked to more aggressive forms of cancer and earlier metastases." (PMID 39063046, 2024). "Gene polymorphisms in MMP-2 and MMP-9 can influence their function, impacting cancer development and progression." (PMID 39063556, 2024). "Next, an online Kaplan-Meier plot was used to assess the predictive value of the PTGS2/ESR2/EGFR/JUN/MMP2 genes’ signature expression level on OS in numerous human cancers." (PMID 39707884, 2024). "The peptide present in DHPDB is cleaved by MMP-2, which is overexpressed in cancer, and the self-assembled structure is decomposed due to DEAP protonation, thereby releasing CXB." (PMID 38255307, 2024). "We further verified the metastatic ability of the cancer cells caused by the LMF exposure by assessing two metastasis-related proteins, matrix metalloproteinases MMP2 and MMP9, which both were significantly increased." (PMID 39336161, 2024). "Many scholars have reported that the expression increase of IL-17 in the cancer tissues can improve cell proliferation resulting in cancer growth or elevating MMP2 and MMP9 production leading to NSCLC metastasis." (PMID 38560562, 2024). "It is well established that MMP2 plays a crucial role in different steps of cancer progression including invasion, migration, proliferation, and apoptosis." (PMID 38978899, 2024). "For example, nanoparticles combined with MMP-2 inhibitors have been reported to improve outcomes in cancer photodynamic immunotherapy." (PMID 38693104, 2024). "Another PT, 6,6′-bieckol, inhibited NF-κB and MMP2/9 expression, which eventually reduced cancer cell migration." (PMID 38671856, 2024). "MMP2 can break the extracellular matrix, which facilitates the migration and invasion of cancer cells." (PMID 39636301, 2024). "Our data showed that RO extracts significantly decreased the quantities of TNFα, VEGFa, COX-2, and MMP2 in A549 cancer cells in combination with 5-FU." (PMID 38918540, 2024).
cancer (continued). "Our results show that TGF-β/TNF-α combined treatment of the cancer cells synergistically increased the expression of MMP-2 and MMP-25 when we compared either treatment of TGF-β or TNF-α." (PMID 39351229, 2024). "The anti-cancer and anti-metastatic properties of genistein result largely from its ability to inhibit MMP-2 and MMP-9, as proven in many studies on various cancer cell lines." (PMID 39335164, 2024). "Among MMPs, MMP-2, -7 and -9 have been reported to promote cancer cell migration and invasion, with MMP-2 and MMP-9 being especially prevalent in PCa progression." (PMID 39063105, 2024). "CAFs also promoted cancer progression, increasing the secretion of matrix metalloproteinase 2 (MMP2), MMP9, vascular endothelial growth factor (VEGF), tumor growth factor-β (TGF-β), and basic fibroblast growth factor (bFGF)." (PMID 38611093, 2024). "Subsequent studies corroborated that eHsp90 interacts with cancer cell secreted MMPs- particularly the inactive zymogen forms of MMP-2 and MMP-9." (PMID 39594828, 2024). "As demonstrated in previous studies, activated STAT3 promotes cancer cell metastasis through transcriptional activation of multiple mediators, including MMP2, MMP9 and EMT-related genes 51-53." (PMID 39113711, 2024). "The self-assembled structure, which contains a peptide that is degraded by MMP-2, selectively releases the loaded drug from cancer cells and activates the immune system." (PMID 38255307, 2024). "Inhibit crucial proteins in OSCC by molecular docking; reducing p38 phosphorylation and downregulating matrix metalloproteinase (MMP)-2 expression; promising candidates for the development of targeted anti-cancer therapies against OSCC." (PMID 39518052, 2024). "The intracellular domain, including Snail and MMP2, activates a gene group that encourages cancer cell invasion." (PMID 38313020, 2024). "Thiazolidinediones have been found to inhibit cancer cell behaviour in various tumour cells via PPARγ‐dependent and PPARγ‐independent mechanisms, such as a decrease of metalloproteinase 2 (MMP2) activity." (PMID 39636301, 2024). "MMP2 was expressed at very low levels in normal tissue and highly expressed in 47.7% of cancer samples." (PMID 39335130, 2024). "MMP-2 and MMP-9 are also involved in cell death by destroying basilar membrane molecules and have been implicated in cancer metastasis and invasion." (PMID 39408655, 2024). "Targeting the regulatory mechanisms of MMP-2, particularly in pathological conditions like fibrosis and cancer, holds significant therapeutic potential but requires a detailed understanding of its complex regulatory network." (PMID 39769454, 2024). "Some authors focused on exploring the diagnostic utility of the serum MMP-2 and MMP-9 levels in OC patients in relation to the clinicopathological features of cancer." (PMID 38673838, 2024). "The co-culture of ASCs with cancer cells leads to increased expression of MMPs, such as MMP-2, MMP-9, and MMP-14, in both ASCs and cancer cells." (PMID 39519109, 2024). "It has been shown that ERK1/2 positively regulates both proliferation-related (e.g. c-Myc, Cyclin D1) and migration-related (e.g. matrix metalloproteinase-2; MMP2) proteins to drive cancer cell progression." (PMID 38311733, 2024). "Other plant extracts have been reported to attenuate the migration and invasion of cancer cells by acting through MMP-2 and MMP-9 reduction." (PMID 38405665, 2024). "Since tumors originating from human or mouse cancer cell lines expressed MMP-2 and MMP-9, we tested the spatial specificity of ACPP cleavage and localization in syngeneic murine tumors grown in immune-competent mice." (PMID 39683778, 2024). "Selenite impedes the invasive capabilities of cancer cells by curtailing the activity of MMP-2 and MMP-9, as well as uPA." (PMID 39839762, 2024).